LASP1 (LIM and SH3 protein 1)
Diseases named in the same sentence as LASP1 in open-access papers (continued):
Sharing a sentence is not in itself a finding about the gene and the disease.
breast carcinoma (continued). "Our data clearly show that the LASP1 gene is not amplified in the vast majority of human breast cancers (only 1 out of 64 cases), suggesting that LASP-1 overexpression is mediated through transcriptional regulation rather than gene amplification." (PMID 20461080, 2010). "Similar to findings in human breast cancer, our immunofluorescence experiments have shown that absence of LASP-1 in focal contacts dramatically influences zyxin distribution." (PMID 17211471, 2007). "By our immunohistochemical stainings LASP-1 was detectable in nuclei of 29% of all investigated breast carcinomas independent of its actual cytosolic expression." (PMID 17956604, 2007). "To further assess the cellular expression pattern of LASP-1, we performed confocal and non-confocal microscopy of immunofluorescence labeled LASP-1 in the breast cancer cell line BT-20." (PMID 17956604, 2007). "Cellular LASP-1 distribution and expression pattern was visualized by immunofluorescence and confocal microscopy and assessed through separate Western blots of nuclear and cytosol preparations of BT-20, MCF-7, MDA-MB231, and ZR-75/1 breast cancer cells." (PMID 17956604, 2007). "The absence of PPP1R14B-AS1 led to the downregulation of LASP1 levels in breast cancer cells." (PMID 37303940, 2021). "This suggests that Let-7a targets will be strong downstream targets of the LASP1-Ago2 interaction as they are upregulated in advanced breast cancer, and miR-100 targets outside of Ago2 itself may not be strong targets." (PMID 32872485, 2020). "MMP regulation by LASP1 is not restricted to breast cancer cells." (PMID 27588391, 2016). "To investigate whether the 3’-UTRs of BIRC5 and LASP1 are functional targets of miR-203 in breast cancer cells, we co-transfected the miR-203 precursor (or control miRNA) and pMIR-BIRC5-3’-UTR plasmid (or mutant) or pMIR-LASP1-3’-UTR plasmid (or mutant) into cells." (PMID 22713668, 2012). "Our results provide evidence that nuclear LASP-1-positivity may serve as a negative prognostic indicator for long-term survival of breast cancer patients." (PMID 20461080, 2010). "LIM and SH3 protein 1 (LASP-1), initially identified from human breast cancer, is a specific focal adhesion protein involved in cell proliferation and migration, which was reported to be overexpressed in 8–12 % of human breast cancers and thought to be exclusively located in cytoplasm." (PMID 17956604, 2007). "In breast cancer metastasis, particularly in Triple Negative Breast Cancer (TNBC), LIM, and SH3 Protein 1 (LASP1) interacts with AGO2 in a C-X-C Motif Chemokine Receptor 4 (CXCR4)-dependent manner." (PMID 40863728, 2025). "LASP-1 is clearly detectable in the nuclei of human breast cancer cell lines MCF-7 and BT-20, while nuclei of MDA-MB231 and ZR-75/1 cells were found to be negative for LASP-1 in the nuclear fraction." (PMID 17956604, 2007). "Western blot analysis verified nuclear LASP-1 localization in MCF-7 and BT-20 cells while breast cancer cell lines MDA-MB231 and ZR-75/1 only displayed a cytosolic but no nuclear LASP-1 localization." (PMID 17956604, 2007). "We therefore performed an immunoprecipitation assay with monoclonal LASP1 antibody and indeed could detect an LASP1-AKT1 interaction in MDAMB-231 breast cancer cells but not in K562 cells." (PMID 32075106, 2020). "Phosphorylation of LASP1 at Ser-146 is not inducing any translocation of the protein to the nucleus and besides, the CML cell lines do not express the LASP1 binding shuttle partner ZO2 as do breast cancer cells." (PMID 24913448, 2014).
colorectal cancer (43 papers, 2012 to 2026). A primary or metastatic malignant neoplasm that affects the colon or rectum. "For example, LASP1 can cause the progression and metastasis of colorectal cancer (CRC), but its mechanism is still unclear." (PMID 36970516, 2023). "Increased LASP1 protein levels were also found in metastatic high-risk prostate carcinomas, metastatic colorectal carcinomas (CRC), in clear cell renal cell carcinoma (ccRCC) tissues and in bladder carcinoma (BC) specimens." (PMID 25622104, 2015). "Recent studies have shown that HSP90 can promote the metastasis of colorectal cancer cells by regulating LASP1 abundance in a PUS7-dependent manner." (PMID 36203415, 2022). "LASP1 is an actin-binding protein and can enhance tumor growth and metastasis in multiple cancers, including nasopharyngeal carcinoma, colorectal cancer, triple-negative breast cancer, and pancreatic ductal adenocarcinoma." (PMID 35846349, 2022). "Multiple reports have shown that LASP1 promotes invasion and metastasis in a variety of tumors including pancreatic cancer, colorectal cancer, and medulloblastoms." (PMID 34288804, 2021). "Our results showed that LASP1 can bind to CCT8, and CCT8 can restore the ability of LASP1 to promote the invasion of colorectal cancer cells." (PMID 34862361, 2021). "LIM and SH3 protein 1 (LASP1) is a metastasis-related protein reported to enhance tumor progression in colorectal cancer (CRC)." (PMID 34862361, 2021). "From literature, miR-133a can inhibit cell growth, migration, metastasis by targeting LASP1 in colorectal cancer." (PMID 34575979, 2021). "LASP1 has been reported to be upregulated in colorectal cancer facilitating cell progression through the PI3K/AKT, TGF‐β/Smad3 signaling pathway." (PMID 33074595, 2020). "Previous studies reported that LASP1 activates the PI3K/AKT pathway in colorectal cancer and gallbladder cancer; notably, The Cancer Genome Atlas (TCGA) dataset analysis showed LASP1 was positively related to the PI3K/AKT pathway." (PMID 29980193, 2018). "In this context, it is interesting to note, that high LASP1 expression was accompanied with downregulated levels of LASP2 in colorectal cancer (CRC) cell lines and tissues." (PMID 30298118, 2018). "Because previous reports have shown that LASP1 has increased expression in colorectal cancer, these results suggest that microbiota exposure may increase the risk for colorectal cancer in individuals carrying the allele associated with higher expression of LASP1." (PMID 27709125, 2016). "LASP-1 is overexpressed in several human malignancies included human metastatic breast cancer, ovarian cancer, colorectal cancer, malignant childhood medulloblastoma, hepatocellular carcinoma, bladder and oral cancer, and prostate carcinoma." (PMID 25760690, 2015). "It is known that the overexpression of VIM is significantly associated with HCC metastasis and it is a circulating molecular biomarker for HCC and that LASP-1 induces TGF-β-mediated EMT transition in human colorectal cancer." (PMID 25760690, 2015). "Previous studies have reported that silencing LASP-1 expression in breast, ovarian and colorectal cancer cell lines leads to reduced cell proliferation and migration." (PMID 24955835, 2014). "Knock-down of LASP-1 by RNA interference resulted in a strong inhibition of proliferation and migration of cancer cells, such as breast, ovarian and colorectal cancer cell lines." (PMID 22897902, 2012). "LIM and SH3 domain protein 1 (LASP1) is a cytoskeleton protein that has been identified to participate in the development of human cancers with several types, and facilitate the growth and invasion of glioma cells and colorectal cancer cells via EMT." (PMID 33722250, 2021).
colorectal cancer (continued). "Another research showed that miR-133a inhibited the MAPK/ERK cascade by targeting the upstream protein LASP1, which could suppress tumor metastasis and growth in colorectal cancer." (PMID 29137432, 2017). "As LASP1 forms complexes with FSCN1 to serve as indispensable actin filament-bundling proteins that stabilize the lamellipodia of cancer cells and has already been demonstrated to promote the metastasis of colorectal cancer, we predicted that LASP1 is another potential target of miR-145." (PMID 27626692, 2016). "LIM and SH3 protein 1 (LASP1) can promote colorectal cancer (CRC) progression and metastasis, but the direct evidence that elucidates the molecular mechanism remains unclear." (PMID 27156963, 2016). "LIM and SH3 protein 1(LASP1) can promote colorectal cancer (CRC) progression and metastasis, but the mechanism remains unclear." (PMID 27181092, 2016). "Furthermore, colorectal cancer cells also show higher expression of LASP1, suggesting that LASP1 plays a similar role in colonocytes." (PMID 27709125, 2016). "Decreased pAKT1-S473 phosphorylation after LASP1 depletion has been observed before in several tumor cell lines, glioblastoma, gall bladder and nasopharyngeal carcinoma, while LASP1 overexpression induces phosphorylation in colorectal cancer cells and non-small cell lung cancer." (PMID 32075106, 2020). "In colorectal cancer, PUS7 facilitates cancer cell migration through the HSP90/PUS7/LASP1 pathway, enhances proliferation via SIRT1 activating the Wnt/β-catenin pathway, and stimulates proliferation and invasion through the PI3K/AKT/mTOR signaling pathway." (PMID 41554761, 2026). "In colorectal cancer (CRC) specifically, miR-133 has been reported to target multiple oncogenic factors including LASP1, TAGLN2, FSCN1, and COL1A1, thereby suppressing proliferation, migration, and invasion." (PMID 41300774, 2025). "As we have a solid research basis on LASP1 in CRC cancer progression, the function of LASP2 was also studied in colorectal cancer." (PMID 28606091, 2017). "Previous studies showed that Lasp1 promoted EMT via inducing phosphorylation of MAPK, PI3K/AKT and Smad signaling in colorectal carcinoma." (PMID 29088849, 2017). "Previous literature has reported that pseudouridine synthase PUS7, through a non-enzymatic pathway, interacts with LASP1, stabilizing the latter and promoting colorectal cancer cell metastasis." (PMID 39247811, 2024). "PUS7 also facilitates the metastasis of colorectal cancer cells by upregulating LASP1 (LIM and SH3 protein 1), independent of PUS7's catalytic activity." (PMID 39175405, 2024). "Additionally, PUS7 regulates its downstream effector LIM and SH3 protein 1(LASP1), which promotes colorectal cancer metastasis." (PMID 36457503, 2022). "In addition, LASP1 was found to facilitate EMT in glioma and colorectal cancer cells, and interact with vimentin in HCC." (PMID 33722250, 2021). "Its involvements in cancer are emerging too: in melanoma by acting on key master regulators of the signaling pathway; in papillary thyroid cancer by sponging hsa-miR-324-3p and up-regulating LIM and SH3 domain protein 1 (LASP1); in colorectal cancer by regulating the miR-132/Derlin-1 pathway." (PMID 32605220, 2020). "For colorectal cancer and medulloblastoma no distinct differentiation between cytosolic and nuclear LASP1 positivity was performed but patient survival was again inversely correlated with global LASP1 expression." (PMID 24980827, 2014). "In this study, through an LC–MS assay, LIM and SH3 protein 1 (LASP1) was identified as a sphingolipid-metabolism-involved protein, and short-chain enoyl-CoA hydratase (ECHS1) was identified as a new LASP1-interacting protein through a protein assay in colorectal cancer (CRC)." (PMID 34615856, 2021).
hepatocellular carcinoma (24 papers, 2010 to 2024). A malignant tumor that arises from hepatocytes. "We also explored the molecular mechanisms associated with the upregulation of vimentin mediated by LASP1 in HBX-positive hepatoma cells." (PMID 33722250, 2021). "Next, we explored the mechanisms associated with the increase of vimentin mediated by LASP1 in HBX-positive hepatoma cells." (PMID 33722250, 2021). "LASP-1 over-expression is also observed in hepatocellular carcinoma (HCC) and associated with poor clinical prognosis of the disease." (PMID 28266596, 2017). "Besides, the biological functions and potential molecular mechanisms associated with vimentin mediated by HBX via LASP1 in hepatoma cells was also investigated." (PMID 33722250, 2021). "Furthermore, we found that vimentin also participates in cellular proliferation and migration mediated by LASP1 in HBX-associated hepatoma cells." (PMID 33722250, 2021). "However, whether these signal pathways are associated with the expressions of vimentin mediated by LASP1 in HBX-positive hepatoma cells is unknown." (PMID 33722250, 2021). "Nuclear localization of LASP1 has since then also been observed in hepatocellular carcinoma, bladder carcinoma and medulloblastoma." (PMID 35507100, 2022). "Our results demonstrated that LASP1 was a pivotal modulator of the molecular characteristics of EMT by regulating vimentin in HBX-positive hepatoma cells." (PMID 33722250, 2021). "When HBX-positive cells with decreased LASP1 were treated with vimentin expression vectors, the migration capability of hepatoma cells was enhanced." (PMID 33722250, 2021). "Transwell and wound healing assays were next utilized to investigate the effect of vimentin in cell migration mediated by LASP1 in HBX-positive hepatoma cells." (PMID 33722250, 2021). "As expected, the results showed that the stability level of vimentin was decreased, and the ubiquitination level of vimentin was enhanced, when HBX-positive hepatoma cells were incubated with LASP1 shRNA." (PMID 33722250, 2021). "The expression of vimentin induced by HBX, and the role of LIM and SH3 domain protein 1 (LASP1) in HBX-induced vimentin expression in hepatoma cells were examined by western blot and immunohistochemistry analysis." (PMID 33722250, 2021). "On the one hand, PI3-K, ERK, and STAT3 signal pathways were involved in the upregulation of vimentin mediated by LASP1 in HBX-positive hepatoma cells." (PMID 33722250, 2021). "Meanwhile, the increased expression of E-cadherin and reduced expression of β-catenin were also found in HBX-positive and LASP1-inhibited hepatoma cells." (PMID 33722250, 2021). "We found that the expressions of vimentin and β-catenin were increased, but the expression of E-cadherin was declined in LASP1-overexpressed hepatoma cells." (PMID 33722250, 2021). "In summary, the present study characterized the expression and associated molecular functions of vimentin mediated by HBX in HCC and identified LASP1 as a regular of vimentin protein expression in HBX-positive hepatoma cells." (PMID 33722250, 2021). "Overall, these findings indicated that the activation of PI3-K, ERK, and STAT3 pathways mediated by LASP1 was responsible for vimentin protein expression in HBX-positive hepatoma cells." (PMID 33722250, 2021). "Recently, nuclear LASP1 distribution was also described for hepatocellular carcinoma (HCC) and is observed in human bladder cancer tissue." (PMID 30298118, 2018). "These were in consistent with prior research that molecular characterization of LASP1 expression revealed Vimentin as its new partner in human hepatocellular carcinoma cells." (PMID 28186968, 2017). "Recent study also proved the vital role of LASP1 in tumor metastasis by working together with Vimentin in hepatocellular carcinoma (HCC) cells." (PMID 27626692, 2016).
hepatocellular carcinoma (continued). "Our findings showed that HBx was able to upregulate the expression of LASP-1 in human hepatoma HepG2 and Huh-7 cells through activation of phosphatidylinositol 3-kinase (PI3-K) pathway." (PMID 22897902, 2012). "Taken together, these results suggested that HBX could interact with vimentin and LASP1, and protect vimentin from ubiquitination and degradation via LASP1 in hepatoma cells." (PMID 33722250, 2021). "We previously demonstrated that HBX could promote the proliferation and migration of hepatoma cells via LASP1." (PMID 33722250, 2021). "Furthermore, our results showed that PI3-K, ERK, and STAT3 pathways were responsible for vimentin expression mediated by LASP1 in HBX-positive hepatoma cells." (PMID 33722250, 2021). "Besides these, vimentin was involved in the growth and migration of hepatoma cells mediated by LASP1 in HBX-positive hepatoma cells." (PMID 33722250, 2021). "Except these, LASP1 has been reported to be capable of interacting with vimentin in hepatoma cells." (PMID 33722250, 2021). "Moreover, abnormal expression of LASP1 was detected in a variety of other cancers, including hepatocellular carcinoma, nasopharyngeal carcinoma, prostate cancer, pancreatic cancer, and ovarian cancer." (PMID 34862361, 2021). "Besides, the effect of HBX on vimentin stability was dependent on the presence of LASP1 protein in hepatoma cells." (PMID 33722250, 2021). "Taken together, these results indicated that HBX could promote the expression of vimentin through LASP1 in hepatoma cells." (PMID 33722250, 2021). "Besides these, the co-location of HBX, LASP1, and vimentin was also found in hepatoma cells based on immunofluorescence assay." (PMID 33722250, 2021). "However, the binding partners involved in the development of HBV-related hepatocellular carcinoma mediated by LASP-1 are not completely understood." (PMID 28266596, 2017). "We speculated that PI3-K pathway may be involved in the HBx-mediated upregulation of LASP-1 in hepatoma cells." (PMID 22897902, 2012). "In addition, the upregulation of LASP-1 mediated by HBx contributed to proliferation and migration of hepatoma cells." (PMID 22897902, 2012). "In summary, our present data demonstrated that HBx upregulated the expression of LASP-1 through PI3-K in promotion of hepatoma cell proliferation and migration, suggesting that LASP-1 might play a critical role in the HBx-associated hepatocarcinogenesis." (PMID 22897902, 2012). "At first, we investigated whether LASP1 could enhance EMT in hepatoma cells." (PMID 33722250, 2021). "Our previous studies indicated that HBX could promote the expression of LASP1 in hepatoma cells." (PMID 33722250, 2021). "We found that LASP1 inhibition could reduce the migration ability of HBX-positive hepatoma cells." (PMID 33722250, 2021). "We examined whether LASP1 contributes to the vimentin expression mediated by HBX in hepatoma cells." (PMID 33722250, 2021). "The role of RanGAP1 in hepatocellular carcinoma is demonstrated by its ability to promote cell migration and invasion through the up-regulation of KMD2A expression or LASP1 SUMOylation." (PMID 38267624, 2024). "Because HBX also interacted with LASP1, we also investigated the effect of HBX on LASP1 stability in hepatoma cells in the present study." (PMID 33722250, 2021).